LIF (LIF interleukin 6 family cytokine)
Diseases named in the same sentence as LIF in open-access papers (continued):
Sharing a sentence is not in itself a finding about the gene and the disease.
cancer (continued). "However, the mechanism underlying the regulation of LIF in cancer has not been elucidated." (PMID 35481460, 2022). "It has been shown that BM-MSCs can enhance angiogenesis by releasing LIF to activate the ERK1/2 pathway and induce cancer cells to express vascular endothelial growth factors." (PMID 35740622, 2022). "A cell-type-specific pathway that contributes to renal cell carcinoma is LIF-induced TFE3 and TFEB expression, which in turn activate E-cadherin in fibroblasts but downregulate E-cadherin in cancer cells." (PMID 35204717, 2022). "For example, both CAFs and cancer cells are able to secrete LIF to activate CAFs and their ECM remodeling that favors CAFs migration together with cancer cells in a combined manner." (PMID 35493456, 2022). "Leukemia inhibitory factor (LIF) is a pleiotropic protein, which is overexpressed in many cancers and plays a carcinogenic role." (PMID 35992780, 2022). "REST target genes upregulated in ER- or TNBCs include MYC, LIF, and EGFR which play significant roles in cancer progression, cell proliferation and endocrine resistance." (PMID 35177031, 2022). "In the Cancer Cell Line Encyclopedia database, IL23A and LIF were found to be highly expressed in CRC cell lines." (PMID 34017356, 2021). "LIF is secreted by stromal cells in the pancreatic TME, which acts specifically on cancer cells to promote tumorigenesis." (PMID 34298706, 2021). "Data of the GEO database revealed that HRAS oncogenic signature were enriched in Gins1 high-expressed cancer cells, and silencing GINS1 decreased RAS, SKP2 and LIF expression in our experiments." (PMID 34414190, 2021). "The following will discuss LIF-LIFR signaling from a general perspective, and then transition to a more precise conversation regarding these signaling pathways within cancer." (PMID 34395259, 2021). "This article aims to review the available data on the role of LIF in PDAC promotion, and to discuss the evidence supporting its potential role as a biomarker and target of effective anti-cancer therapy in this setting." (PMID 33630157, 2021). "Described by others in the past as enigmatic and paradoxical, LIF and LIFR are expressed in a diverse array of cells in the body, and the narrative surrounding them in cancer-related processes has been vague, and at times even contradictory." (PMID 34395259, 2021). "The function of LIF:LIFR signaling in stemness and progression of cancers has been studied previously." (PMID 32651426, 2020). "Increasing V1 or LIF and V2 or TGFβ are signs of fibroblast activation and transformation of NAF to CAF, also overexpression of U2 or CXCL12 is sign of cancer promoting role of CAF and invasiveness of cancer cells." (PMID 32384110, 2020). "Leukemia inhibitory factor (LIF) regulates several features of cancers and cancer stem cells (CSCs) through binding to LIF receptor (LIFR)." (PMID 32651426, 2020). "However, the mechanism through which LIF promotes cancer motility remains unclear." (PMID 31973037, 2020). "Pro-inflammatory cytokines, such as leukemia inhibitory factor (LIF) and interleukin-6 (IL-6), are secreted by both cancer cells and CAFs, and mediate the epigenetic modification of CAFs." (PMID 32546182, 2020). "Several current partially successful approaches for cancer therapy are in agreement with the i-CSC/p-ESC model, targeting crucial factors common to embryos and tumors, such as HSP70, HLA-G, ID, LIF/LIFr, and CD44." (PMID 30899759, 2019). "Collectively, our in vitro studies demonstrated that OSCC cell lines stimulate LIF production in NHDFs, and that NHDF-derived LIF participates in cancer-cell migration and invasion." (PMID 29444110, 2018). "Our results demonstrated that OSCC cells stimulate fibroblasts to produce leukemia inhibitory factor (LIF), which, in turn, participates in cancer-cell invasion; this finding therefore suggests one potential therapeutic target in OSCC." (PMID 29444110, 2018).
cancer (continued). "The induction of miR-21 by LIF mediates the promoting effect of LIF on EMT; blocking miR-21 function greatly abolished the promoting effect of LIF on EMT and migration ability in cancer cells." (PMID 26716902, 2016). "A similar FR901228 treatment of the carcinoma cells further enhanced LIFR expression and LIF-dependent signaling." (PMID 16271139, 2005). "The treatment induced the expression of LIFRα and established a LIF-dependent STAT3 and ERK signaling that was comparable to the level observed in the carcinoma cells." (PMID 16271139, 2005). "Therefore, further investigation of cytoplasmic LIF in HCC progression and the development of effective small‐molecule drugs targeting cytoplasmic LIF in cancer therapy represents an effective treatment strategy and clinical direction." (PMID 40416597, 2025). "Mechanistically, LIF activates the AKT pathway, which facilitates the translocation of the glucose transporter Glut1 to the plasma membrane, enhancing glucose uptake and promoting glycolysis in cancer cells." (PMID 39857986, 2025). "Moreover, LIF produced by pancreatic stellate cells (PSCs) in PDAC activates STAT3 and is involved in the regulation of cancer cell differentiation and epithelial-mesenchymal transition." (PMID 39169307, 2024). "The expression of leukaemia inhibitory factor (LIF) is a novel feature of the IPASS, as LIF has not previously been identified as a prominent feature of the TIME in paediatric cancer." (PMID 37013636, 2023). "Therefore, we focused on upregulated secretome genes that included several known cachexia mediators described in pan-cancer and NSCLC, such as IL6, IFNG, LIF, CCL2, and CSF3." (PMID 36774484, 2023). "These cells were confirmed to maintain GFP expression and proliferate without LIF indicating the change of miPSC’s phenotype after co-injection with cancer cells." (PMID 35063003, 2022). "Several tumors exhibit upregulated JAK/STAT, ERK/MAPK, and PI3K/AKT signaling via autocrine or paracrine activation of LIF/LIFR GP130, and this pathway significantly contributes to EMT in several cancers, disease progression, and a poorer relapse-free survival in several cancers." (PMID 35847866, 2022). "Finally, these data suggest that cannabigerol and IFN-γ exert their anti-cancer properties via the inhibition of STAT3 (upregulated by IL-11 and LIF) and c-Jun/AP-1 (downregulated by Pentraxin2/SAP), respectively." (PMID 36923728, 2022). "miR-637 blocks cancer cell cycle progression by targeting HEMGN and LIF." (PMID 36175921, 2022). "Also, simulation results succeeded to reproduce the behavior of SMAD7, TGFβ, LIF, and CXCL12 molecules in both cancer cell and CAF." (PMID 36171274, 2022). "Mouse models have been primarily used for studying the roles of LIF within cancers, and there is a lack of studies using nonhuman primate models to further investigate these findings and provide additional evidence for potential clinical trials." (PMID 35204717, 2022). "Leukemia Inhibitory Factor (LIF) and its receptor (LIFR), part of the interleukin-6 (IL-6) cytokine family, make up one such ill-defined piece of the puzzle connecting inflammation to cancer." (PMID 34395259, 2021). "These pancreatic myofibroblast cells and any secreted LIF they produce are therefore largely missing from flank xenograft models of human cancer, where any mouse-derived LIF that is produced will not bind and activate human LIFR43." (PMID 33846527, 2021). "Of note, cancer cells were also positive for LIF, SEMA7A, and HAS1, while they were negative for αSMA." (PMID 32931156, 2020). "Besides LIF and TGFβ, there are some key regulatory molecules such as CXCL12 and SLIT2 in the model which are cancer progression and prevention players, respectively." (PMID 32384110, 2020).
cancer (continued). "The process requires some crucial interacting factors, such as LIF/LIFr, IL6/IL6r, IL10, IL11, GP130, JAK, and STAT3, and correlated signal pathways, leading to the switch from anchorage-independent to anchorage-dependent growth, both in embryos and cancer." (PMID 30899759, 2019). "Moreover, targeting the GDNF–RET axis as well as LIF inhibition reduces PNI both in vitro and in vivo, while targeting Neurturin impairs PNI and cancer aggressiveness." (PMID 31248001, 2019). "On the contrary, orthologs of some cancer-related genes like oncostatin M (OSM) or leukemia inhibitory factor (LIF) have not yet been identified in zebrafish." (PMID 28894696, 2017). "The likely decision to tend toward a more cancer stem cell-like phenotype rests on ZEB1 not binding the LIF promoter." (PMID 28246407, 2017). "Importantly, blocking miR-21 function greatly abolished the promoting effect of LIF on EMT and the migration ability of cancer cells." (PMID 26716902, 2016). "LIF-activated dermal fibroblasts gain cellular contractility and provide ECM remodeling via a crosstalk between the JAK1/STAT3 and RhoA/ROCK/MLC2 signaling pathways, reciprocally resulting in cancer cell invasion in vitro and in vivo." (PMID 25853091, 2015). "Whereas LIF does not affect cell proliferation or invasion of cancer cells, it protects malignant cholangiocytes from chemotherapy-induced apoptosis via a STAT3- and MAPK-independent, PI3K/AKT-dependent Mcl-1 activation." (PMID 26296968, 2015). "LIF and LIFR/gp130 were found to be expressed in most of 30 human carcinoma cell lines." (PMID 26296968, 2015). "It is currently unclear whether LIF activates the AKT-mTOR pathway to promote tumorigenesis and metastasis in other types of cancers." (PMID 24553191, 2014). "Furthermore, Shh-activated fibroblasts increased the secretion of factors such as LIF and VEGF that have an important effect on cancer cells." (PMID 23667589, 2013). "In carcinoma cell lines, the major trends included a strong STAT3 activation by LIF (ADLC, H125), an increased (ADLC, H23) or decreased STAT3 activation by IL-6 (H125, H324), a decreased ERK activation by EGF (H522), and a treatment-independent, constitutive activation of the ERK pathway (H23)." (PMID 16271139, 2005). "These pathways are activated by both cancer cells and inflammatory stromal components, emphasizing the necessity for a comprehensive understanding of the interplay between angiogenic (VEGF, HGF) and immunoregulatory (IL-7, LIF) signals to fully comprehend the mechanisms of immune escape." (PMID 41597220, 2026). "They secrete TGF-β, leukemia inhibitory factor (LIF), growth arrest-specific protein 6 (GAS6), fibroblast growth factor 5 (FGF5), growth differentiation factor 15 (GDF15), and hepatocyte growth factor (HGF), which drive the invasive and proliferative behaviors in cancer cells." (PMID 40313969, 2025). "LIF is a highly pleiotropic member of the IL-6 family of cytokines, upon binding to the LIFR complex promotes the crosstalk between the extracellular matrix (ECM) and cancer cells and mediates the transition through a pro-invasive phenotype of stromal fibroblasts and cancer cells." (PMID 37945798, 2024). "Interestingly, COAD was the cancer type where RNF43, CYP2S1 and LIF showed the highest expression, suggesting that these three genes’ cancer-specific functions might be attributed to their adjacent super-enhancers." (PMID 37207350, 2023). "Exploring the roles of LIF in normal physiology and non-cancer pathologies can give important insights into how it may be dysregulated within cancers, and the possible effects of this dysregulation." (PMID 35204717, 2022).
cancer (continued). "Furthermore, LIF is commonly upregulated in carboplatin and paclitaxel resistant cells, suggesting that LIF/LIFR overexpression might contribute to cancer chemoresistance." (PMID 35847866, 2022). "Since there are no studies available on cancer survivors, it is challenging to conclusively answer the question of the relationship between age of treatment and LIF expression and what role it may play in the morbidity of different diseases among CCS." (PMID 35626130, 2022). "Moreover, it has been shown that leukemia inhibitory factor (LIF) and the signal transducer and activator of transcription-3 (STAT-3) activates mitogen-activated protein kinase 5 (MEK5), which subsequently activates ERK5 in normal and cancer cells." (PMID 34298754, 2021). "Moreover, isolated cells from malignant tumors expressed cancer stem cell markers and had ability to survive without LIF in culture media, while miPSCs failed to survive without LIF." (PMID 31905766, 2019). "We first assessed whether, similar to CAF isolated from head and neck, lung and breast human carcinomas (HN-CAF, Lu-CAF and Br-CAF, respectively), the long-term LIF or TGFβ-activated human dermal fibroblasts (hDF_LIF or hDF_TGFβ) constitutively retain their proinvasive properties." (PMID 26667266, 2015). "Human and zebrafish genomes are 70% similar based on conservation of individual genes, with several cancer-associated genes found in mammals but not in the zebrafish, including BRCA1, p16 (CDKN2A), BRCA1, LIF, OSM, IL6 and PML (G.D. and J.N.B., unpublished observation)." (PMID 24973744, 2014). "Finally, increased LIF and VEGF secretion by Shh-activated fibroblasts may affect the stemness of cancer cells." (PMID 23667589, 2013). "Notably, LIF‐induced STAT3 signaling also participates in HCC development, exemplified by arsenic trioxide, which simultaneously suppresses the LIF/JAK1/STAT3 and NF‐kB signaling pathways, thereby promoting cancer stem cell differentiation and impeding HCC development." (PMID 40416597, 2025). "In addition, studies using in vitro laboratory models of LIF signaling within cancer or other disease states may not accurately reflect what occurs within the highly complex, three-dimensional environment of the human body." (PMID 35204717, 2022). "Moreover, the production of TGFβ, leukemia inhibitory factor (LIF), growth arrest-specific protein 6 (GAS6), fibroblast growth factor 5 (FGF5), growth differentiation factor 15 (GDF15), and hepatocyte growth factor (HGF) promotes invasive and proliferative behavior in cancer cells." (PMID 34646829, 2021). "However, LIF secretion may be stimulated by pro-inflammatory cytokines, such as IL-6, IL-1 and tumor necrosis factor (TNF)-α, leading to elevated serum LIF levels in cancer patients." (PMID 26296968, 2015). "The modeling procedure starts with presenting nonlinear dynamics of cancer cells and CAFs using ordinary differential equations based on TGFβ, CXCL12, and LIF signaling pathways." (PMID 36171274, 2022). "Cells expressing GFP were selected by treating cells with 1.5 μg/ml of puromycin without leukemia inhibitory factor (LIF) so that the residual miPCs, cancer cells, and host-derived cells should be removed." (PMID 35063003, 2022). "In cLIF cancer cells, the LIFR level was constitutively high, indicating they were not responsive to exogenous LIF stimulation." (PMID 30504771, 2018). "To evaluate cellular response to exogenous LIF stimulation, we treated cancer cells with recombinant human LIF pre-labeled with ATTO 488 and found that cLIF cells appeared resistant to the uptake of LIF, unlike that observed in WT or LIF+/− cells." (PMID 30504771, 2018).
cancer (continued). "In trophoblast cell lines, LIF is reported to increase the proliferation and invasion of JEG-3 choriocarcinoma cells via STAT323, though in a non-cancer derived HTR8 trophoblast cell line, LIF promoted proliferation via ERK1/2, but not STAT324." (PMID 26272398, 2015). "However, some cancer‐related genes, such as breast cancer 1 early onset (BRCA1) and leukemia inhibitory factor (LIF), are not conserved." (PMID 41108536, 2025). "The results of these studies demonstrate that while LIF and LIFR are expressed in non-neoplastic pancreases, the two genes are differently regulated in the cancer tissues: thus, while LIFR is downregulated in PADC cancer in comparison with the adjacent tissue, LIF undergoes an opposite modulation." (PMID 36359879, 2022). "However, in our experimental conditions, LIF failed to influence their gene expression levels, meaning the anti-apoptotic effect of LIF is unlikely to be related to a dedifferentiation of CCA cells to a cancer stem cell phenotype." (PMID 26296968, 2015).